NXPH4 (neurexophilin 4)
Description:
May be signaling molecules that resemble neuropeptides and that act by binding to alpha-neurexins and possibly other receptors.
Synonyms: NPH4
Tractability: Antibody: UniProt places it where antibodies can reach, with high confidence; UniProt predicts a signal peptide or a membrane-spanning region; its Gene Ontology location is reachable by antibodies, with medium confidence. PROTAC: ubiquitination databases record sites on it.
Gene: Protein-coding gene on chromosome 12 (57,216,794 to 57,226,449, forward strand). Ensembl gene ENSG00000182379.
Subcellular location: Secreted
Gene Ontology:
Molecular function: signaling receptor binding
Biological process: neuropeptide signaling pathway; modulation of chemical synaptic transmission
Cellular component: extracellular region; GABA-ergic synapse; synapse
Genetic constraint (gnomAD): Loss-of-function variants: 8 observed, 13.85 expected, observed/expected ratio (o/e) 0.58, 90% interval 0.34 to 1.04. The synonymous counts are far from expectation, so gnomAD's model fits this gene poorly and the ratio says little. Missense variants: 370 observed, 326.98 expected, observed/expected ratio (o/e) 1.13, 90% interval 1.04 to 1.23. Synonymous variants: 191 observed, 147.24 expected, observed/expected ratio (o/e) 1.3, 90% interval 1.15 to 1.46.
Homologues: Orthologues: chimpanzee NXPH4 (99% identical), macaque NXPH4 (96% identical), pig NXPH4 (92% identical), dog NXPH4 (90% identical), rat Nxph4 (90% identical), mouse Nxph4 (89% identical). Paralogues in human: NXPH2 (40% identical), NXPH1 (37% identical), NXPH3 (33% identical).
Diseases named in the same sentence as NXPH4 in open-access papers:
NXPH4 is named in the same sentence as 38 diseases in open-access papers, as found by Europe PMC text mining. Sharing a sentence is not in itself a finding about the gene and the disease. The quoted sentences say what the papers report.
bladder cancer (7 papers, 2022 to 2025). "Recent investigations have unveiled a multifaceted association between NXPH4 and various cancers, including lung cancer, kidney cancer, and bladder cancer." (PMID 39164641, 2024). "Therefore, we further conducted experiments to explore the underlying mechanism of the influence of NXPH4 on bladder cancer." (PMID 35954445, 2022). "Additionally, in this way, we first found the possible relationship between NXPH4 and the survival outcome of patients with bladder cancer and revealed the underlying mechanism with a series of experiments." (PMID 35954445, 2022). "NXPH4 overexpression has been shown to induce gemcitabine resistance in bladder cancer by increasing ROS and glycolysis levels." (PMID 40061896, 2025). "Survival analyses confirmed that NXPH4 was closely associated with OS and PFS in bladder cancer patients, and positively correlated with poor prognosis." (PMID 39559360, 2024). "The Kaplan–Meier analysis showed that even in different groups of patients with bladder cancer the patients with lower levels of NXPH4 had better prognoses than patients with higher levels." (PMID 35954445, 2022). "Through wound healing assays, transwell invasion assays, and plate clone formation assays, we found that NXPH4 promoted the proliferation, migration, and invasion of bladder cancer cells." (PMID 35954445, 2022). "The immunohistochemistry (IHC) results of cancer or corresponding adjacent normal tissues also suggested that NXPH4 was upregulated in bladder cancer tissues." (PMID 35954445, 2022). "After the knockdown of the expression of NXPH4 in bladder cancer cell lines, we found that only the expression of NDUFA4L2 was influenced while others were not." (PMID 35954445, 2022). "Taken together, these results suggest that NDUFA4L2 is an important target for NXPH4 to function in GEM-R bladder cancer cells." (PMID 35954445, 2022). "We found that patients with high disease progress and high grades of bladder cancer had higher expression levels of NXPH4 in contrast to those patients with complete responses and lower grades of bladder cancer." (PMID 35954445, 2022). "Through bioinformatics analysis, we first found that NXPH4 was independently related to the prognosis of patients with bladder cancer." (PMID 35954445, 2022). "Through an analysis of the transcriptome data of patients from TCGA with 33 kinds of cancers, we found the distinct expression patterns of NXPH4 across multiple cancers and specifically explored its clinical relevance in bladder cancer." (PMID 35954445, 2022). "Consistent with our previous in vitro results, the overexpression of NXPH4 significantly abolished the inhibitory effects of GEM treatment in parental bladder cancer cell-derived groups, as indicated by the increased tumor size and tumor weight." (PMID 35954445, 2022). "Recently, a study on the effect of NXPH4 in the prognosis and immune cell infiltration of bladder cancer has been published." (PMID 36245978, 2022). "In order to deeply explore the mechanism of NXPH4 in bladder cancer, we searched for possible targets of NXPH4 by bioinformatic analysis." (PMID 35954445, 2022). "Our results imply that NXPH4 contributes to the proliferation, migration, and invasion of bladder cancer by maintaining the stability of NDUFA4L2 and consequently activating reactive oxygen species and glycolysis." (PMID 35954445, 2022). "The results showed that the expression of NXPH4 and N stage were independent indicators for the survival outcomes of patients with bladder cancer." (PMID 35954445, 2022). "We performed xenograft mouse models to further reveal the effects of the NXPH4/NDUFA4L2 pathway on chemotherapy resistance in bladder cancer in vivo." (PMID 35954445, 2022). "Similarly, NXPH4 regulates cell cycle dynamics and tumor progression in non-small cell lung cancer and bladder cancer." (PMID 39164641, 2024).
bladder cancer (continued). "To identify whether NXPH4 affects the drug sensitivity of bladder cancer cell lines, we compared the expression of NXPH4 between parental T24/5637 and T24GEM-R/5637GEM-R cells with qPCR and WB." (PMID 35954445, 2022). "Considering that NDUFA4L2 is associated with oxidative stress and glycolysis in various diseases, we speculated that NXPH4 promotes drug resistance in bladder cancer cells by regulating oxidative stress and glycolysis through NDUFA4L2." (PMID 35954445, 2022). "Meanwhile, the cell viability of GEM-R bladder cancer cells induced by NXPH4 overexpression could be inhibited by 2-DG, BAY-876 (inhibitor for GLUT1), or oxamate (inhibitor of LDHA)." (PMID 35954445, 2022). "According to the results above, we can speculate that higher expression levels of NXPH4 may be closely related to worse survival outcomes (overall survival, disease-specific survival, progress-free interval) for patients with bladder cancer." (PMID 35954445, 2022). "In summary, our research found a new molecule, NXPH4, which influences the prognosis of patients with bladder cancer, and revealed that NXPH4 promotes progression, metastasis, and gemcitabine resistance in bladder cancer by enhancing glycolysis through modulating the expression of NDUFA4L2." (PMID 35954445, 2022). "According to the results above, we can speculate that the expression level of NXPH4 may be closely related to the survival outcomes of patients with bladder cancer." (PMID 35954445, 2022). "Thus, the results above elucidated that NXPH4/NDUFA4L2 was a potential target for the treatment of GEM-resistant bladder cancer." (PMID 35954445, 2022). "To further investigate the biological role of NXPH4 in gemcitabine-resistant bladder cancer cell lines, we knocked down the expression of NXPH4 in T24GEM-R and 5637GEM-R cell lines and found that it reversed the chemoresistance of T24GEM-R and 5637GEM-R cells as shown by GEM-R cell survival." (PMID 35954445, 2022). "Therefore, we conducted a series bioinformatic analyses and functional experiments to reveal the novel role of NXPH4 in bladder cancer." (PMID 35954445, 2022). "Finally, the expression of NXPH4 was validated in clinical tissue specimens and bladder cancer cell lines by immunohistochemistry and qRT-PCR." (PMID 35758021, 2022). "Generally speaking, these results indicate that NXPH4 is overexpressed in bladder cancer tissues." (PMID 35954445, 2022). "We found NXPH4 not only influenced the proliferation, migration, invasion ability of cancer cells, but also affected the level of glycolysis and reactive oxygen species and further promoted the gemcitabine resistance of bladder cancer." (PMID 35954445, 2022). "Notably, the expression of NXPH4 was significantly higher in T24GEM-R and 5637GEM-R cells than that in parental cells, which was consistent with the elevated NXPH4 expression in bladder cancer tissues of patients resistant to chemotherapy with gemcitabine." (PMID 35954445, 2022). "In addition, it was found that compared with patients with lower grades of bladder cancer, patients with higher grades of bladder cancer had higher levels of NXPH4." (PMID 35954445, 2022). "Moreover, we confirmed that the mRNA and protein levels of NXPH4 were higher in bladder cancer cell lines (BIU-87, 5637, RT112, and T24) than in the normal bladder cell line SV-HUC-1 by qRT-PCR and WB." (PMID 35954445, 2022). "To test whether ROS are responsible for the enhanced tumorigenic properties of NXPH4 in bladder cancer, we blocked the production of ROS with the antioxidant N-acetylcysteine (NAC)." (PMID 35954445, 2022). "This indicated that NXPH4 may exert an influence on the prognosis of patients with bladder cancer." (PMID 35954445, 2022). "However, the potential role of NXPH4 in bladder cancer (BCa) remains to be explored." (PMID 35758021, 2022).
bladder cancer (continued). "Therefore, the ROS-induced NXPH4/↓circHIPK3/↑miR-29b-3p/↑miR-193a-3p/↓LOXL4/↓SRSF2 axis may represent a potential mechanism through which circHIPK3 downregulation contributes to gemcitabine resistance in bladder cancer." (PMID 40061896, 2025). "The results showed that compared with normal samples, the NXPH4 expression was obviously higher in tumor samples, including HCC, bladder cancer, colon cancer, breast cancer, and gastric cancer." (PMID 36245978, 2022). "Taken together, these results suggest that NXPH4 regulates intracellular ROS and promotes GEM resistance in bladder cancer cells in a glycolytic manner." (PMID 35954445, 2022). "Interestingly, the knockdown of NXPH4 significantly inhibited, while the overexpression of NXPH4 promoted, the glycolysis level of GEM-R bladder cancer cell lines." (PMID 35954445, 2022). "NXPH4, on the other hand, has not been associated with RCC carcinogenesis but may be a biomarker for bladder cancer." (PMID 36899967, 2023).
hepatocellular carcinoma (4 papers, 2022 to 2025). A malignant tumor that arises from hepatocytes. "Recent studies demonstrated that elevated expression of NXPH4 in human cancer cell lines and human serum is linked to hepatocellular carcinoma (HCC), suggesting this gene is a potential biomarker for the pathology." (PMID 40489480, 2025). "The overexpression of NXPH4 is associated with unfavorable prognoses in patients with CRC and hepatocellular carcinoma." (PMID 39164641, 2024). "Further experiments indicated that NXPH4 promotes the proliferation, migration, and invasion of CRC and hepatocellular carcinoma (HCC)." (PMID 39164641, 2024).
breast carcinoma (3 papers, 2022). "NXPH4 is a mitochondria-related core gene involved in the progression of breast cancer." (PMID 35205681, 2022). "Genes extracted from the gene expression omic dataset that play key roles in the development of breast cancer are CDCA5, IL17RB, MUC2, NOD2, and NXPH4." (PMID 35205681, 2022). "Current studies show that EZH2/NXPH4/CDKN2A axis can participate in regulating the proliferation and migration of non-small-cell lung cancer cells revealing a poor prognosis in the prognosis model of breast cancer." (PMID 36245981, 2022).
esophageal cancer (3 papers, 2022 to 2024). A primary or metastatic malignant neoplasm involving the esophagus. "A pan-cancer analysis demonstrated the consistent upregulation of NXPH4 across various DSCs, suggesting its diagnostic potential in cholangiocarcinoma, esophageal cancer, liver cancer, and gastric cancer." (PMID 39164641, 2024).
liver cancer (3 papers, 2022 to 2024). An epithelial or non-epithelial malignant neoplasm that arises from the liver. "Dysregulation of NXPH4 in pan-cancer suggests its potential as a diagnostic and prognostic marker for certain cancers, including colon and liver cancer." (PMID 38613793, 2024).
non-small cell lung carcinoma (3 papers, 2022 to 2024). A group of at least three distinct histological types of lung cancer, including non-small cell squamous cell carcinoma, adenocarcinoma, and large cell carcinoma. "NXPH4 shows a higher expression level in LIHC, BLCA, and non-small cell lung cancer, but the cause of NXPH4 dysregulation remains unclear." (PMID 38613793, 2024).
breast invasive carcinoma (2 papers, 2022 to 2024). "Tissue validation results have demonstrated a higher expression level of NXPH4 in cancers such as cervical squamous cell carcinoma, endocervical squamous cell carcinoma, cholangiocarcinoma, invasive breast cancer, colorectal adenocarcinoma, and oesophageal cancer." (PMID 38613793, 2024). "NXPH4 levels were observed in the initial stages of Breast invasive carcinoma (BRCA), Cervical squamous cell carcinoma and cervical adenoma (CESC), COAD, and Liver hepatocellular carcinoma (LIHC), and its expression increased significantly as pathological and clinical stages progressed." (PMID 38613793, 2024).
colon cancer (2 papers, 2022 to 2024). "Our study specifically investigated the association between NXPH4 gene expression and the prognosis of colon cancer." (PMID 38613793, 2024). "Knockdown of NXPH4 significantly suppresses proliferation, invasion, and migration of colon cancer cell lines HT-29 and HCT116, as validated by functional assays." (PMID 38613793, 2024). "Functional assays (CCK-8, plate clonogenicity assay, wound healing assay, and Transwell assay) confirmed the impact of NXPH4 on proliferation, invasion, and migration of colon cancer cells." (PMID 38613793, 2024). "Western blot further confirmed the higher expression of NXPH4 in colon cancer." (PMID 38613793, 2024). "Western blot verified differential expression of NXPH4 in colon cancer." (PMID 38613793, 2024). "Importantly, functional studies have shown that NXPH4 can promote colon cancer progression." (PMID 38613793, 2024). "Moreover, in vitro studies confirmed the oncogenic effect of NXPH4 in colon cancer." (PMID 38613793, 2024).
colorectal cancer (2 papers, 2024). A primary or metastatic malignant neoplasm that affects the colon or rectum. "Firstly, the current research observed the presence of NXPH4 protein in samples obtained from patients with colorectal cancer as well as from healthy individuals." (PMID 38613793, 2024). "The findings indicated a substantial increase in NXPH4 protein expression levels within colorectal cancer tissues, which was consistent with previous research outcomes." (PMID 38613793, 2024). "By conducting a wound healing assay, it was observed that sh-NXPH4 had a considerable inhibitory impact on the migration ability of colorectal cancer cell lines HT29 and HCT116." (PMID 38613793, 2024). "In order to examine the biological role of NXPH4 in colorectal cancer, a GSEA enrichment analysis was carried out." (PMID 38613793, 2024). "The current study used the TIDE algorithm to predict the sensitivity of colorectal cancer patients to immunotherapy and found that patients with high NXPH4 expression had higher TIDE scores, which implies less sensitivity to immunotherapy." (PMID 38613793, 2024). "Thus, NXPH4 expression might partially indicate the immune status of the tumor microenvironment and predict the sensitivity of colorectal cancer patients to immunotherapy." (PMID 38613793, 2024). "Subsequently, colorectal cancer cell lines HT29 and HCT116 were transfected with sh-NC and sh-NXPH4, and their impact on cell proliferation, migration, and invasion was assessed." (PMID 38613793, 2024).
Glioblastoma multiforme (2 papers, 2022 to 2024). "At the OS level, the outcomes of the univariate Cox analysis highlighted a link between elevated NXPH4 expression levels and worse OS in ACC, BLCA, BRCA, COAD, Glioblastoma multiforme (GBM), KIRP, LIHC, SKCM, and UCEC." (PMID 38613793, 2024).
lung carcinoma (2 papers, 2022). "Recent research found that NXPH4 promotes the proliferation and migration of lung cancer cells." (PMID 36212461, 2022).
Thyroid carcinoma (2 papers, 2022 to 2024). "The study highlighted a higher expression of NXPH4 in almost all cancers except Kidney renal papillary cell carcinoma (KIRP), Acute Myeloid Leukemia (LAML), Skin Cutaneous Melanoma (SKCM), Thyroid carcinoma (THCA), and thymoma (THYM)." (PMID 38613793, 2024).
Anxiety (1 paper, 2019). Intense feelings of nervousness, tension, or panic often arise in response to interpersonal stresses. "Since Nxph4 is expressed in many regions of the amygdala, we tested the mice for anxiety-like behavior using the elevated plus maze assay." (PMID 31524598, 2019).
Cognitive impairment (1 paper, 2021). Abnormal cognition is characterized by deficits in thinking, reasoning, or remembering. "The MOFA model also identified molecules previously associated with cognitive impairment, such as dynein light-chain 2, cytoplasmic (DYL2), and neurexophilin-4 (NXPH4)." (PMID 33794997, 2021).
lentivirus infection (1 paper, 2019). Virus diseases caused by the Lentivirus genus. "To test our hypothesis, we expressed Nxph4-3xFLAG-mCherry in primary cultured cortical neurons using lentivirus infection." (PMID 31524598, 2019). "When we over-expressed an mCherry fused Nxph4-4Q-HA (mutated Nxph4 without glycosylation) in primary cultured cortical neurons through lentivirus infection, we could barely detect its expression in the cell lysates, suggesting that, in neurons, Nxph4 is not stable without glycosylation." (PMID 31524598, 2019).
liver abscesses (1 paper, 2025). "However, further studies are needed to understand the NXPH4 role in liver abscesses in cattle." (PMID 40489480, 2025).
liver disease (1 paper, 2022). "A biomarker panel consisting of HMMR, NXPH4, PITX1 and THBS4 was defined and validated as an effective serologic diagnostic tool for the detection of HCC patients among liver disease patients through the use of simple ELISAs." (PMID 35456219, 2022).
retinoblastoma (1 paper, 2024). A malignant tumor that originates in the nuclear layer of the retina. "In GBM, BRCA, HNSVC, Retinoblastoma (RB), and Uveal melanoma (UM), high NXPH4 expression was mainly positively linked to Angiogenesis and Differentiation and negatively linked to DNA damage, DNA repair, EMT, apoptosis, cell cycle, and invasion." (PMID 38613793, 2024).
urothelial carcinoma (1 paper, 2023). A malignant neoplasm derived from the transitional epithelium of the urinary tract (urinary bladder, ureter, urethra, or renal pelvis). "In urothelial carcinoma, NXPH4 affects glycolysis and cell proliferation by maintaining the stability of NDUFA4L2." (PMID 36899967, 2023).